INS (insulin)
Diseases named in the same sentence as INS in open-access papers (continued):
Sharing a sentence is not in itself a finding about the gene and the disease.
Obesity (continued). "Firstly, several major CVD risk factors such as blood lipids, insulin, and proinflammatory cytokines may play as additional modulators in determining the association between PA, obesity, and increased CIMT, and they should be accounted for in a future study." (PMID 30155478, 2018). "In addition, persistently high insulin was associatedwith a more proneness to developing hypertension, dyslipidemia and obesity in youngadults." (PMID 30365811, 2018). "Similarly, a study performed on children with obesity underlined the potential role of K121Q ENPP1 polymorphism in not only early perturbations of glucose and insulin metabolism but also subsequent obesity development." (PMID 30338250, 2018). "Epidemiological evidence suggest a correlation between inflammation and insulin resistant states such as obesity, but the underlying mechanisms are largely unknown." (PMID 31565650, 2018). "Type 2 DM is associated with obesity and the secretion of proinflammatory cytokines by adipocytes (especially central obesity), which contribute to insulin resistance and β-cells injury (high levels of reactive oxygen species - ROS), compromising insulin action." (PMID 30405072, 2018). "The majority of genes linked to either risk of T2DM or risk of Obesity, with a smaller number to more discrete phenotypes (fasting insulin, fasting glucose or circulating lipids—reflective of smaller GWAS samples and/or phenotypes with greater random and technical error)." (PMID 29986096, 2018). "Similarly, for obesity, significant associations and risk factors include insulin, c-peptide of insulin, albumin, and uric acid." (PMID 29650030, 2018). "Likewise, obesity associated increases in circulating insulin, leptin, and adiponectin were ameliorated to a similar extent by hypoxia and by restricted feeding." (PMID 30210452, 2018). "The role of obesity in laminitis is unclear, but as insulin concentrations correlate positively with obesity, weight loss as a secondary benefit of SGLT-2 inhibition could be desirable in certain cases." (PMID 30212530, 2018). "Obesity is a relevant causal factor in the etiology of insulin-action resistance." (PMID 29601492, 2018). "The effects of endothelium‐specific CYP2J2 overexpression on aging‐associated obesity, inflammation, and peripheral insulin resistance were evaluated by assessing metabolic parameters in young (3 months old) and aged (16 months old) adult male Tie2‐CYP2J2‐Tr mice." (PMID 29318723, 2018). "However, these observational studies did not document and control for all lifestyle-dependent factors of obesity risk, all of which impact insulin secretion." (PMID 30541568, 2018). "Prolonged sedentariness in children and adolescents is associated with increased body fat in athletes, obesity and its persistence in childhood, poor cardiorespiratory fitness, lower insulin sensitivity, higher blood pressure and total cholesterol, and compromised academic achievement." (PMID 30404165, 2018). "In addition, IGFBP-2, the mostly highly accumulated from C5aR1−/− adipocytes, is associated with reduced susceptibility to obesity and improved insulin sensitivity, further supporting the injurious role of C5aR1 in adipose inflammation and dysfunction." (PMID 30294325, 2018). "They speculate that HPI is associated with reduced risk for obesity, thus not only reducing the likeliness for acidic reflux, but also the insulin level in the blood." (PMID 29938864, 2018). "Tissue specific TLR4 effects have been studied in the past and confirmed observation from global deletions, e.g. myeloid-specific (as well as global) TLR4-deficiency improves insulin sensitivity and inhibits obesity-induced tissue inflammation in HFD and lipid infusion models." (PMID 29426925, 2018). "Another study reported increased apelin-12 serum concentration in patients with obesity and obesity-related insulin resistance, which could be caused by impaired insulin sensitivity." (PMID 29875677, 2018).
Obesity (continued). "Indeed, in different cancers, such as breast, colon, or prostate cancer, hyperinsulinemia and obesity induced by insulin and IGF1/2 are associated with poor prognosis." (PMID 30186236, 2018). "In addition, the consumption of a high amount of glucose in the diet increases the risk of obesity, dyslipidemia, heart disease, resistance to insulin, oxidative stress, and apoptosis and caspase-3 activation." (PMID 29558444, 2018). "Characterized as a cluster of signs associated with laminitis susceptibility, EMS may present physiologically as obesity, insulin dysregulation and hyperlipemia." (PMID 30001422, 2018). "This gene regulates insulin sensitivity and predisposition to obesity." (PMID 30223795, 2018). "Indeed, PTP1B locus maps to chromosome 20 in the region q13.1–q13.2, which is a region recognized as a quantitative trait locus linked to insulin and obesity." (PMID 30558294, 2018). "Numbers of evidence indicated that PAQR3-deficient mice are resistant to high-fat-diet (HFD)-induced obesity and hepatic steatosis, accompanied by improvement of insulin resistance and insulin signaling, which suggests that PAQR3 plays a vital role in the regulation of glycolipid metabolism." (PMID 29930535, 2018). "An ethnicity specific effect of higher insulin responsiveness was identified in African American women compared with European American women, which might be further relevant for obesity predisposition." (PMID 29780358, 2018). "An imbalance between NE and A1AT has recently been implicated in obesity induced insulin signaling and energy metabolism, suggesting this pair maybe involved in the metabolic cascade initiating T2DM." (PMID 30298053, 2018). "In urine, change in hippurate, a metabolite previously found to be inversely associated with metabolic syndrome risk, gut microbiota richness, and obesity, was positively associated with improvement in IS, specifically, with a decrease in plasma insulin, HOMA-IR and FIRI." (PMID 30804813, 2018). "A decreased resistin concentration by knocking out the resistin encoding gene or blocking resistin by antibody could protect against obesity-associated hyperglycemia, which is mainly due to recovering the response of the liver to insulin." (PMID 29785210, 2018). "Taken together, our data indicate that NECC2 is a component of adipocyte caveolae that is regulated in response to obesity and associated metabolic complications, and support a role for this protein as a molecular scaffold modulating insulin signal transduction at these membrane microdomains." (PMID 30160359, 2018). "Interestingly, recent evidences in mice and human suggested that the adipose tissue inflammation associated with obesity, in particular the T cell imbalance, and the impairment in insulin sensitivity, persist even after weight reduction." (PMID 29867762, 2018). "Reduced insulin sensitivity has been correlated with changes in the immune status in pregnancy, including elevated levels of circulating pro-inflammatory cytokines that are thought to drive obesity-associated metabolic inflammation." (PMID 30197635, 2018). "The roles of these genes are complex and interdependent, being linked to different cornerstones in obesity development, such as appetite behavior, control of food intake and energy balance, insulin signaling, lipid and glucose metabolism, metabolic disorders, adipocyte differentiation, and so on." (PMID 30338250, 2018). "CC-chemokine receptor 2 (CCR2), a receptor for monocyte chemoattractant proteins (MCPs), plays a pivotal role in the entry of innate immune cells into tissue and influences systemic insulin resistance and adipose tissue inflammation associated with obesity in high-fat-fed murine models." (PMID 29967759, 2018). "Moreover, two separate studies indicated a positive association between the elevated serum vaspin levels with obesity and impaired insulin sensitivity." (PMID 29644922, 2018).
Obesity (continued). "Physical activity has been proposed to influence breast cancer risk through several mechanisms, including weight loss, obesity prevention, reduce sex hormones, insulin, and insulin-like growth factor levels, and induce immune system function and mechanism of DNA repair." (PMID 30194548, 2018). "In addition, obesity, an important cardiovascular risk, is modulated by the regulatory axis of PPARs/miRNAs, including adipogenesis, adipocyte dysfunction, insulin resistance, and macrophage polarization in adipose tissue." (PMID 30622558, 2018). "Specifically, we aimed to assess whether habitual dietary intakes of both specific macronutrients and food groups are associated with insulin sensitivity and insulin secretion over a 2-y period in children with a family history of obesity." (PMID 30383280, 2018). "This suggests that the diet‐induced increase in insulin levels may predispose the individual to obesity." (PMID 30353684, 2018). "The ATX–LPA axis is not only implicated in obesity, but may play an important role in the regulation of glucose homeostasis and insulin sensitivity." (PMID 29570618, 2018). "Loss of autophagy is a critical component of defective insulin action seen in obesity." (PMID 29552281, 2018). "Obesity is associated with substantial metabolic and endocrine abnormalities, including changes in sex hormone metabolism, insulin and insulin-like growth factor signaling, as well as adipokines or inflammatory pathways (Calle & Kaaks, 2004; Renehan, Zwahlen & Egger, 2015)." (PMID 29576948, 2018). "Moreover, there is evidence in favor of a role of insulin in promoting obesity-associated adipose tissue inflammation." (PMID 29867762, 2018). "Teasing apart the relative contribution of physical, weight-dependent mechanisms from physiological-dependent mechanisms is inherently difficult due to the close relationship between obesity and its associated changes in glycemic control, insulin action, and leptin signaling." (PMID 30127766, 2018). "We believe that obesity-related genetic variants also modulate glucose–insulin secretion." (PMID 30170548, 2018). "Moreover, both conventional and AgRP-restricted P2Y6-deficient animals exhibit reduced obesity as well as improved whole-body insulin sensitivity when exposed to long-term HFD feeding." (PMID 29619754, 2018). "In addition, large for gestational age (LGA) infants are predisposed to obesity and cardiovascular disease later in life as they develop a high fat ratio and reduced insulin sensitivity." (PMID 29809159, 2018). "Obesity has been reported to be associated with delayed insulin absorption." (PMID 30116732, 2018). "Moreover, use of jet injection has also been reported to be beneficial in terms of diminishing the obesity-associated delay in insulin absorption compared to pen injections." (PMID 30116732, 2018). "Associations persisted after adjustment for obesity, fasting insulin and fasting glucose." (PMID 29875472, 2018). "On the other hand, CR may impact the obesity-cancer pathway, by reducing serum insulin, leptin, and associated inflammation by limiting NFκβ—related gene expression." (PMID 30202241, 2018). "Ghrelin is also implicated in the inhibition of insulin stimulated glucose uptake during obesity." (PMID 29596390, 2018). "Ageing, like obesity, is often associated with alterations in metabolic and inflammatory processes resulting in morbidity from diseases characterised by poor metabolic control, insulin insensitivity, and inflammation." (PMID 29479350, 2018). "At the same time, obesity is associated with a decrease in adipose tissue secretion of adiponectin, and adipokine that improves hepatic insulin sensitivity, has several anti-inflammatory properties including production of anti-inflammatory cytokines, and has protective effects in the liver." (PMID 28929125, 2017).
Obesity (continued). "Disruptions in insulin signal transduction in the hypothalamus caused by low-grade inflammation associated with the increase of adipose tissue constitute an important trigger for the obesity genesis." (PMID 29062272, 2017). "In addition, relative tissue hypoxia in obesity can itself lead to increased systemic inflammation and loss of insulin sensitivity, both of which exert deleterious effects on muscle regeneration." (PMID 28725215, 2017). "The resulting surge of cytokine secretion, particularly TNFα, is known to be a cause of obesity-associated insulin resistance in the adipose tissue by promoting serine phosphorylation of IR substrate-1, thereby blocking the propagation of downstream insulin signaling." (PMID 28959684, 2017). "It is crucial to understand the mechanisms underlying impaired insulin signaling during inflammatory processes, to advance in the treatment of obesity and to help alleviate people suffering from degenerative disorders associated with inflammatory markers in the brain." (PMID 28677618, 2017). "Failure in glucose response to insulin is a common pathology associated with obesity." (PMID 29228058, 2017). "Understanding the insulin signaling pathway involved in cell metastasis and progestin resistance will be critical for the development of new intervention strategies to prevent or treat EC associated with obesity." (PMID 28112250, 2017). "However, certain racial ethnicities known to have very high levels of circulating insulin are also known to be at increased risk for the development of obesity." (PMID 28466412, 2017). "In combination, these methods could direct future studies towards furthering the understanding of the role played by regional adipose depots in obesity-associated pathologies such as laminitis, insulin dysregulation and pedunculated lipoma." (PMID 28296956, 2017). "Loss of skeletal muscle mass may impede insulin-mediated glucose disposal and exacerbate obesity-related IR." (PMID 29108358, 2017). "Further, obesity was associated with hyperinsulinemia and caused abnormalities in the insulin signaling pathway, which may impact the expression and localization of insulin-related factors, such as InsR, in breast cancer." (PMID 29234306, 2017). "We have previously shown that six weeks of nopal consumption significantly reduced hepatic triglyceride content, improved hepatic insulin signaling and biomarkers of oxidative stress, as well as liver function in a genetically predisposed model of obesity and hepatic steatosis (Zucker fa/fa rats)." (PMID 28196086, 2017). "Whilst the exact mechanisms remain unclear, obesity has been associated with an increased risk for the development of insulin dysregulation and the common systemic condition, laminitis, which initially presents as severe foot pain." (PMID 28296956, 2017). "In summary, we report here that lungs of obese mice display nitrosative-associated impairment of insulin signaling, which may amplify asthma exacerbations associated with obesity." (PMID 29229986, 2017). "Bioactive mediators derived from ω-3 PUFAs, SPMs, including the resolvins E1 (RvE1) and D1 (RvD1), protectin D1 (PD1) and maresin 1 (MaR1) were found to limit obesity associated inflammation, switch macrophage polarization to M2 and improve insulin sensitivity in type 2 diabetes." (PMID 28993702, 2017). "Obesity is associated with increased insulin levels, which affects CD4+ T cells." (PMID 28651594, 2017). "In addition, obesity is suggested to exaggerate aging processes, and aging is associated with impaired insulin signaling, which causes an increase in blood glucose levels." (PMID 28686216, 2017). "Hyperphagia and obesity could be, at least in part, caused by impaired response to insulin of nodose ganglion neurons." (PMID 28966594, 2017).
Obesity (continued). "Reprogramming from inflammatory Mpro towards alternative Manti macrophages might represent a promising strategy to recover whole body insulin sensitivity that would prevent fatal diseases associated with obesity." (PMID 28233125, 2017). "Thus, these cell-type specific regulations by IKKβ appear to produce regional and systemic effects on energy homeostasis and insulin sensitivity culminating to obesity-associated IR." (PMID 28797077, 2017). "IL-1RA and hs-CRP were associated with adverse changes in insulin sensitivity and obesity-related traits and with total mortality (hazard ratio, 1.13; 95% confidence interval, 1.07 to 1.20; and hazard ratio, 1.08; 95% confidence interval, 1.04 to 1.11, respectively)." (PMID 28911155, 2017). "Thus, hypothalamic inflammation impairs the effects of insulin and leptin, contributing not only to hyperphagia and obesity development but also to the associated dysregulation of glucose homeostasis." (PMID 28592656, 2017). "Subsequently, as menopause could be associated with BCa, obesity, and glucose/insulin metabolism, we subdivided both groups by menopausal state." (PMID 29113405, 2017). "However, high-fat-diet-induced obesity is not only associated with a central resistance to insulin and leptin." (PMID 28592656, 2017). "Therefore, we examined the effects of Reb-A on insulin action, circadian rhythms, and susceptibility to diet-induced obesity." (PMID 28475596, 2017). "HSD2 activity was elevated in severe obesity and negatively associated with insulin sensitivity." (PMID 28430825, 2017). "Obesity and insulin treatment seem to have greater impact on cancer risk among women." (PMID 28978007, 2017). "Hyperleptinaemia is typically associated with hyperphagic and/or diet-induced obesity also accompanied by hyperinsulinaemia as its levels are correlated with fat mass and acts centrally to decrease appetite similar to insulin." (PMID 28421113, 2017). "Furthermore, persistently high insulin levels over time were associated with a higher probability of developing hypertension, dyslipidemia and obesity in young adults." (PMID 28226031, 2017). "In SCD null mice, it was observed that diet-induced or leptin deficiency-induced obesity was prevented due to reduced body adiposity and improved insulin sensitivity, suggesting SCD as a potential therapeutic target for metabolic complications associated with obesity." (PMID 28621759, 2017). "Moreover, high insulin sensitivity and resistance to obesity has been reported in PTP1B deficient mice undergoing through insulin and glucose tolerance tests." (PMID 28933230, 2017). "Whereas red and processed meat is positively associated with obesity, which may contribute to the causal pathway of T2D, the mechanism by which the consumption of meat may influence fasting glucose and insulin concentrations is more complex." (PMID 28397016, 2017). "Although some obesity-related metabolic factors like adipocytokine levels, insulin resistance, intestinal microbiota, and chronic inflammation are believed to relate obesity and cancer, the underlying pathophysiological mechanisms linking obesity and cancer still remained unresolved." (PMID 28357137, 2017). "In addition, even cats with genetically linked obesity can regain insulin sensitivity after weight loss." (PMID 28629451, 2017). "Alterations in central and peripheral GC production and sensitivity are common in obese humans and in rodent models of obesity, which contribute to fat accumulation in hepatic cells and increased visceral depots and may cause peripheral insulin resistance." (PMID 28727846, 2017). "Interestingly, the major cellular source of AT IL-17 has been reported to be γδT cells rather than αβT cells, and IL-17-deficient mice are more susceptible to HFD-induced obesity, but remain insulin sensitive." (PMID 29186929, 2017).